SYP (synaptophysin)
Diseases named in the same sentence as SYP in open-access papers (continued):
Sharing a sentence is not in itself a finding about the gene and the disease.
tumor (continued). "Tumor cells were weakly positive for synaptophysin and PAX8 but negative for markers commonly used to distinguish thymic, germ cell, and metastatic carcinomas." (PMID 40421964, 2025). "Immunostaining of the tumor cells was positive for MNF-116 and patchily positive for p40, while negative for leukocyte common antigen (LCA (CD45)), S100, smooth muscle actin (SMA), thyroid transcription factor 1 (TTF-1), and synaptophysin." (PMID 41625888, 2025). "By using immunohistochemical techniques, the authors found alterations in the concentrations of these brain molecules; specifically, the authors found that peri-tumoural areas responded with an increase in MAP2, GFAP, VWF, and synaptophysin compared to control brain areas." (PMID 40806177, 2025). "The tumor cells were negative for cytokeratin, synaptophysin, and chromogranin, ruling out NET and confirming the diagnosis of pancreatic PEComa." (PMID 41246713, 2025). "Tumor sections were stained with hematoxylin and eosin (H&E), and immune-stained for clinically relevant biomarkers, including the primary markers for ADC (TTF1 and Napsina), SCC (P63), as well as LCNEC (CD56, Synaptophysin, Chromogranin)." (PMID 39528952, 2024). "Most of the tumor cells were positive for the glial fibrillary acidic protein (GFAP), CD34 (diffuse cytoplasmic and membranous positivity), with focal expression of Neu-N and synaptophysin on immunohistochemical analysis (IHC)." (PMID 39409964, 2024). "In all conditions, the xenografted tumor stained positively for synaptophysin and staining for CgA was not noted." (PMID 39649120, 2024). "These tumor cells were also positive for synaptophysin and CD56 but negative for other neuroendocrine markers, including chromogranin A, INSM1, and SSTR2A." (PMID 39439633, 2024). "Tumor cells showed positive staining for synaptophysin, chromogranin, and CD56, while negative staining was observed for keratin, CD99, desmin, and myogenin." (PMID 39677122, 2024). "All PGLs were histopathologically confirmed and showed a typical morphology and immunohistochemical profile (positive reaction for chromogranine and/or synaptophysin in tumor cells and for S100 in sustentacular cells; negative reaction for cytokeratin)." (PMID 39335150, 2024). "Immunohistochemical examinations demonstrated positive staining of the tumor cells for cytokeratin, synaptophysin and chromogranin A, and negative for smooth muscle actin, desmin, S-100." (PMID 38152101, 2023). "Tumor cells are positive for chromogranin A, synaptophysin, and GATA3, while consistently keratin negative." (PMID 36941503, 2023). "For example, highly discordant results were seen in the d14 CSF sample from patient 1, with 253–328 hGEs/mL of each SV target, radiology supporting post-operative residual tumor tissue, but with negative cytology including synaptophysin staining." (PMID 37046633, 2023). "Furthermore, the ADRN marker synaptophysin, which was efficiently suppressed by ISX in culture was detected in tumor tissue of both treatment groups at the end of the experiment." (PMID 36755960, 2023). "One tumor expressed in addition AE1/AE3, MUC4, synaptophysin, chromogranin, and ALK." (PMID 37097347, 2023). "Immunophenotypically, the tumor was positive for Cytokeratins Oscar and 7, GATA3, GCDFP, HER2, and an androgen receptor but negative for CK20, S100, p40, Melan A, CDX2, TTF1, ER, SATB2, DOG1, synaptophysin, and chromogranin." (PMID 37886914, 2023). "Unexpectedly, immunostainings highlighted tumor components displaying a robust and diffuse GFAP immunoreactivity, usually not present in MB, along with tumor areas displaying a classical immunoreactivity for Synaptophysin." (PMID 36941703, 2023). "The tumor was positive for chromogranin and synaptophysin while these markers were negative in another case of FAP-associated aggressive CMV-PTC." (PMID 36864485, 2023).
tumor (continued). "Immunohistochemically, the tumor cells were positive for CK, calretinin, D2-40, WT-1, and vimentin, and negative for Paird box 8, synaptophysin, chromogranin-A, inhibin-α, S-100, Melan-A, HMB45, and CD34." (PMID 38115250, 2023). "The insulin-secreting tumor was 10-mm in diameter and consisted microscopically of atypical cells positive for chromogranin A, synaptophysin and insulin but negative for glucagon and somatostatin." (PMID 37563593, 2023). "The tumor displays diffuse positivity for SYP, somatostatin, and the less consistently positive or absent CgA." (PMID 36830839, 2023). "Tumor cells showed immunoreactivity for β-catenin, progesterone receptor and vimentin, and were negative to synaptophysin immunostaining." (PMID 38132247, 2023). "The tumour cells revealed focal cytoplasmic expression of calretinin and synaptophysin, and they were negative for S100, HMB45, melan A, and chromogranin." (PMID 36604647, 2023). "Moreover, it has been shown that a small proportion of CRPC tumour cells acquire a neuroendocrine phenotype with neuronal marker expression, including chromogranin A (CHGA), synaptophysin (SYP) or enolase-2 (ENO2)." (PMID 37875732, 2023). "Tumor cells are usually negative for cytokeratin, epithelial membrane antigen, synaptophysin, chromogranin, INSM1, inhibin, calretinin, and SF1." (PMID 36428715, 2022). "Synaptophysin was not expressed in patient L4 diagnostic TB, while it was detected in 60% of tumor cells in the TB at progression, in 40% of CDX tumor cells, and in 25% of the cell line." (PMID 35511434, 2022). "Immunohistochemical examination of these cells showed that the tumor cells were positive for synaptophysin and partially positive for CD56, and negative for chromogranin A and CAM5.2." (PMID 35235080, 2022). "According to histological assessments, there were no statistical differences in tumor grade, mitotic rate, lymphovascular invasion, and immunohistochemical staining for chromogranin A (CgA) and synaptophysin (Syn) between the two groups (all P > 0.05)." (PMID 36632622, 2022). "One marker for neuroendocrine differentiation, synaptophysin, was positive in two cases (patient 5 and 8), in a pan-cytokeratin negative tumor with epithelioid morphology and a pan-cytokeratin negative tumor with solid morphology." (PMID 35864317, 2022). "The tumor cells were focally positive for synaptophysin and pan-cytokeratin, but negative for CD56 and chromogranin." (PMID 36033527, 2022). "By immunohistochemistry (IHC), tumor cells were diffusely positive for vimentin, variably for synaptophysin, S-100, and NSE, and focally for NeuN; they were negative for GFAP and CK AE1/AE3." (PMID 36090160, 2022). "Tumor cells in MCC typically express markers of neuroendocrine and epithelial differentiation, such as neuron-specific enolase (NSE), CD56, chromogranin A, synaptophysin, and low molecular weight cytokeratins (CK8, CK18, CK19, CK20), CAM 5.2, and AE1/AE3." (PMID 36612102, 2022). "The remaining SCNEC case was negative for synaptophysin but immunoreactive for CD117 in more than 90% of tumor cells, being classified as NED." (PMID 35626098, 2022). "No synaptophysin expression was observed in immunoblasts or other B-, T-, and histiocytes in the tumor." (PMID 36401284, 2022). "Tumor cells were positive for pan-cytokeratin (Pan CK), synaptophysin, vimentin, and S100 (focal) and negative for CD45, CD99, and desmin." (PMID 36259025, 2022). "While lactate did not appear to promote gross tumour cell proliferation as judged by numbers of synaptophysin-positive cells, we found that lactate enhanced the survival of these cells (or, although less likely, the expression of synaptophysin)." (PMID 36178902, 2022). "This tumor was positive for AE1/AE3, CEA, CK20, and synaptophysin." (PMID 35154929, 2022). "Thereafter, immunohistochemical staining revealed that the tumor cells were diffuse positive for synaptophysin and CD56 and negative for chromogranin A." (PMID 35653037, 2022).
tumor (continued). "Immunohistochemistry for the tumor cells was positive for pancytokeratin and cytokeratin 7, partially positive (up to 20%) for cytokeratin 20 and CDX2, and negative for estrogen receptors, monoclonal carcinoembryonic antigen (CEA), and synaptophysin." (PMID 35664390, 2022). "Furthermore, the tumor cells strongly expressed CD56 and synaptophysin and showed a Ki-67 proliferation rate of 40%." (PMID 36207130, 2022). "Tumor cells were focally positive for anti-CD31 (an endothelial marker) and anti-synaptophysin (a marker protein for neuroendocrine cells and neoplasms) immunohistochemistry staining, but negative for CD56 and chromogranin." (PMID 34837560, 2021). "Even if platelet-expressed synaptophysin (pSyn) was not shown to be correlated with age, sex, comorbidities, and medication, pSyn was correlated with the staining intensity in the tumor tissue." (PMID 34064565, 2021). "The tumor lacked contrast enhancement on MRI and demonstrated juxtanuclear dot-like immunoreactivity for synaptophysin which is a feature not previously reported in the literature." (PMID 33786244, 2021). "Most tumor cells of the neuroendocrine component were immunoreactive for CAM.5.2, cytokeratin (CK) 7, CK AE1/AE3, synaptophysin, chromogranin A, parathormone, GATA3, and parafibromin, whilst they were negative for thyroglobulin, TTF1, calcitonin, glucagon, and S100." (PMID 32506375, 2021). "Later, this type of tumor was termed atypical MTC because its immunohistochemical stain is negative for calcitonin but positive for neuroendocrine markers such as chromogranin A (CgA), synaptophysin, and neuron specific enolase (NSE)." (PMID 34803914, 2021). "Immunohistochemistry showed that the tumor cells were positive for calcitonin, chromogranin A, synaptophysin, CD56, and TTF-1, but negative for other lineage-specific markers." (PMID 34838061, 2021). "Of note, this initially EWSR1 rearrangement negative case was positive for keratin (diffuse) and synaptophysin, however it is also noteworthy that this patient was an 11-year-old boy with a femur tumor." (PMID 34698236, 2021). "The tumor cells were positive for synaptophysin and negative for chromogranin with a post-treatment Ki-67 proliferation index of 5%." (PMID 34479480, 2021). "The tumors from which these organoids were derived were heterogeneous, containing both synaptophysin-positive and -negative tumor cells." (PMID 33776923, 2021). "A few tissues within the tumor express synaptophysin without chromogranin-A, which is a neuroendocrine marker." (PMID 33157911, 2020). "The tumor cells possessed neuroendocrine immunophenotype (NSE and synaptophysin positivity)." (PMID 33375764, 2020). "The tumor cells were now negative for Chromogranin A but positive for synaptophysin and pan-cytokeratins, and the Ki-67 index was consistently 90% in all three metastatic lesions." (PMID 32854635, 2020). "On immunohistochemical examination, the tumor cells stained positive for the anticytokeratin antibodies AE1 and AE3 (on part of the surface layer) and for S-100, and partially positive for the neural cell adhesion molecule (CD56) and synaptophysin." (PMID 33025168, 2020). "Tumor cells stain positive for vimentin, S-100 protein, and SOX10; neuroendocrine markers such as CD56, synaptophysin, and NSE may also be positive." (PMID 33025168, 2020). "The tumour was positive for CD99, ERG, CD56, Synaptophysin, PanCK, Cam5.2." (PMID 32450834, 2020). "Further, it was tested negative for CK7 and Synaptophysin, characterizing the tumor as a colorectal AC." (PMID 32927768, 2020).
tumor (continued). "The tumor cells were negative for epithelial membrane antigen, synaptophysin, periodic acid-Schiff (PAS), and pituitary hormones (adrenocorticotropic hormone, human growth hormone, and prolactin)." (PMID 31689841, 2019). "Immunohistochemistry revealed that the majority of tumor cells were positive for chromogranin A (CgA) and Synaptophysin (Syn), but negative for cytokeratin markers (CKs), including CK7 and CK20." (PMID 31038858, 2019). "Immunohistochemical examination revealed that the tumor cells were positive for the neuroendocrine markers chromogranin A and synaptophysin and negative for gastrin, glucagon, somatostatin, VIP, insulin, and serotonin." (PMID 29218566, 2018). "The tumor cells were negative for synaptophysin, SMA (smooth muscle actin), TTF-1 (thyroid transcription factor-1), Chromogranin A, desmin, GFAP, WT-1 (Wilm’s tumor gene-1), HBME-1 (Hector Battifora mesothelial epitope-1)." (PMID 30285886, 2018). "The tumor cells were positive for synaptophysin and weakly positive for NCAM, but negative for chromogranin A. Epithelial markers (AE1/AE3 and CAM5.2) accentuated intracytoplasmic globules." (PMID 29938394, 2018). "In less differentiated neoplasms (G3) of the colon and rectum the staining for either synaptophysin or CgA was mostly focal or negative (50% and 55.6%) but less intense compared to the well-differentiated tumors." (PMID 29232390, 2017). "The tumor cells in the gallbladder are slightly positive for synaptophysin and CD56, but negative for chromogranin A." (PMID 27842605, 2016). "Immunohistochemistry revealed that the tumor was positive for S-100 and negative for synaptophysin, chromogranin A, and pan keratin (AE1/AE3)." (PMID 27832806, 2016). "The tumor cells immunestained was positive for HMB-45, focally positive for c-Kit (CD117), and negative for vimentin, S-100, AE1/AE3, CK-7, CK-18, CD-10, RCC antigen, CgA, DOG-1, EMA, smooth muscle actin, and synaptophysin." (PMID 27858882, 2016). "The tumor itself was negative for S100/chromogranin/synaptophysin and CD45/CD20, thus ruling out the small round blue cell tumors: pPNET and lymphoma, respectively." (PMID 27610254, 2016). "Immunohistochemically, the tumor stained positive for CD56, chromogranin A, and synaptophysin." (PMID 27457078, 2016). "Histologic examination revealed small, round to oval tumor cells arranged in cords or nests, containing hyperchromatic nuclei and mitotic figures; the tumor was positive for synaptophysin and CD56 and negative for chromogranin A expression." (PMID 27818885, 2016). "On immunohistochemical study, the tumor cells showed positive staining for chromogranin and negative staining for synaptophysin." (PMID 27457076, 2016). "The tumor of the patient presented here was negative for S100, chromogranin, and synaptophysin, suggesting that the EES diagnosis was favored over pPNET." (PMID 27610254, 2016). "By immunohistochemical examination, the tumor was strongly positive for HMB-45, focally positive for c-Kit (CD117), and negative for vimentin, S-100, AE1/AE3, CK-7, CK-18, CD-10, RCC antigen, CgA, DOG-1, EMA, smooth muscle actin (SMA), and synaptophysin." (PMID 27858882, 2016). "Immunohistochemically, negative staining of tumor cells with alpha inhibin, synaptophysin, and chromogranin was helpful to exclude these tumors." (PMID 27747121, 2016). "We also observed that the tumor was positive for S-100 which is mainly present in neurons, chondrocytes, adipocytes, and pigment cells, and negative for synaptophysin, chromogranin A, and pan keratin (AE1/AE3)." (PMID 27832806, 2016).
tumor (continued). "In contrast, LCTs and TARTs frequently differ in terms of tumor uni/bilaterality at presentation, tumor uni/multifocality, tumor location in the testis, Reinke crystal prevalence, lipofuscin prevalence, serum ACTH, serum testosterone, tumor responsiveness to ACTH, and synaptophysin immunoreactivity." (PMID 26351608, 2015). "Immunohistochemistry was performed which revealed that the tumor cells were strongly positive for desmin and vimentin and negative for calretinin, inhibin, chromogranin, synaptophysin, S100, pan keratin, and CD68." (PMID 25685588, 2015). "Immunohistochemically, the tumor cells were positive for prolactin, chromogranin-A, and synaptophysin, but were negative for glial fibrillary acidic protein, S-100 protein, epithelial membrane antigen, and vimentin." (PMID 26228535, 2015). "Tumor cells were positive for periodic acid-Schiff reaction and immunoreactive for glycoprotein C99 and gene NKX2.2, as well as the neuroendocrine markers, CD56 and synaptophysin." (PMID 25608963, 2015). "We found that the Tang classification and tumor staging are important prognostic factors along with negative/ focally positive synaptophysin in tissue specimen and non-radical surgery, while the Ki-67 index has no prognostic value." (PMID 25671432, 2015). "The tumor cells were negative for synaptophysin, chromogranin, and cytokeratin 20 by immunohistochemistry, findings which argue against the possibility of primary or metastatic neuroendocrine carcinoma." (PMID 24555117, 2014). "Focal synaptophysin and fascicles of GFAP-immunopositive tumor were noted." (PMID 24321241, 2014). "Synaptophysin, a marker for tumors of neuronal origin, was used as a negative control and, as expected, was negative in tumor tissue." (PMID 25516216, 2014). "Immunohistochemistry showed the tumour cells to be positive for synaptophysin, vimentin, and melan-A and negative for chromogranin." (PMID 24716005, 2014). "Immunohistochemical evaluation also showed the same expression pattern as the tumor from the surgery in 2007, with a positive immunoreaction for synaptophysin and a negative reaction for GFAP." (PMID 23840986, 2013). "GSCC is unique in its positive reactions to synaptophysin and chromogranin A, although 10-20% of GSCCs demonstrate negative reactions for these tumor markers." (PMID 24099520, 2013). "Depending on the degree of neuroectodermal differentiation, the tumor cells may also express neuron-specific enolase (NSE), synaptophysin and S-100 protein." (PMID 25206203, 2013). "Histology showed the lesion to be a completely excised, well differentiated NET with relatively uniform tumour cells, immunopositive for chromogranin-A, synaptophysin and CD56; no detectable mitoses were seen." (PMID 21435225, 2011). "The tumor cells were focally positive for EMA but did not stain positively for synaptophysin, chromogranin, CK7, CK20, TTF-1, GCDFP, P63 or type IV collagen." (PMID 21244696, 2011). "Of interest, in addition to nestin the patient's recurrent tumor showed a propensity toward differentiation along neural lines, as demonstrated by increased expression of other neural markers such as CD56 or neural cell adhesion molecule and synaptophysin." (PMID 21494688, 2011). "Tumour cells were immunoreactive for chromogranin-A and synaptophysin, but not for CD56 or serotonin." (PMID 21435225, 2011). "Neural differentiation markers to CD56 and synaptophysin were expressed in recurrent tumor in the plasmalemmal and cytoplasmic compartments (not shown)." (PMID 21494688, 2011). "Chromogranin A immunostaining was negative and only 1% of the tumours were synaptophysin immunopositive." (PMID 20462442, 2010). "All tumours producing hCGderived molecules were negative for the concomitantly analyzed neuroendocrine markers chromogranin A, synaptophysin and neuron-specific enolase (NSE)." (PMID 21918707, 2010).